RIOK2 (RIO kinase 2)
Description:
Serine/threonine-protein kinase involved in the final steps of cytoplasmic maturation of the 40S ribosomal subunit. Involved in export of the 40S pre-ribosome particles (pre-40S) from the nucleus to the cytoplasm. Its kinase activity is required for the release of NOB1, PNO1 and LTV1 from the late pre-40S and the processing of 18S-E pre-rRNA to the mature 18S rRNA. Regulates the timing of the metaphase-anaphase transition during mitotic progression, and its phosphorylation, most likely by PLK1, regulates this function.
Synonyms: RIO2; FLJ11159
Tractability: Small molecule: a structure with a bound ligand is known; a high-quality ligand is known; it belongs to a druggable protein family. Antibody: the Human Protein Atlas places it where antibodies can reach. PROTAC: it is named in the literature on targeted protein degradation; ubiquitination databases record sites on it; a small molecule that binds it is known.
Target class: Atypical protein kinase RIO2 subfamily; Atypical protein kinase RIO family; Kinase; Enzyme; Protein Kinase; Atypical protein kinase group
Gene: Protein-coding gene on chromosome 5 (97,160,867 to 97,183,289, reverse strand). Ensembl gene ENSG00000058729.
Subcellular location: Cytoplasm
Subcellular location (Human Protein Atlas): Cytosol; Plasma membrane
Pathways (Reactome):
Metabolism of RNA: Major pathway of rRNA processing in the nucleolus and cytosol
Gene Ontology:
Molecular function: protein binding; protein serine kinase activity; protein kinase activity; ATP binding; catalytic activity; protein serine/threonine kinase activity
Biological process: maturation of SSU-rRNA; positive regulation of ribosomal small subunit export from nucleus; positive regulation of rRNA processing; regulation of mitotic metaphase/anaphase transition; ribosomal small subunit biogenesis
Cellular component: cytoplasm; preribosome, small subunit precursor; cytosol; nucleoplasm; nucleus
Genetic constraint (gnomAD): Loss-of-function variants: 30 observed, 40.34 expected, observed/expected ratio (o/e) 0.74, 90% interval 0.56 to 1.01. The upper end of that interval is the gene's LOEUF score, 1.01, which puts it in group 4 of 6, group 1 being the genes least tolerant of losing a copy. Missense variants: 421 observed, 511.77 expected, observed/expected ratio (o/e) 0.82, 90% interval 0.76 to 0.89. Synonymous variants: 161 observed, 176.74 expected, observed/expected ratio (o/e) 0.91, 90% interval 0.8 to 1.04.
Homologues: Orthologues: chimpanzee RIOK2 (99% identical), macaque RIOK2 (97% identical), rabbit RIOK2 (85% identical), dog RIOK2 (85% identical), guinea pig RIOK2 (84% identical), mouse Riok2 (83% identical), rat Riok2 (82% identical), tropical clawed frog riok2 (66% identical), zebrafish riok2 (65% identical), Drosophila melanogaster RIOK2 (45% identical), Caenorhabditis elegans riok-2 (41% identical). Paralogues in human: RIOK1 (19% identical), ATMIN (13% identical), RIOK3 (12% identical).
Diseases named in the same sentence as RIOK2 in open-access papers:
RIOK2 is named in the same sentence as 41 diseases in open-access papers, as found by Europe PMC text mining. Sharing a sentence is not in itself a finding about the gene and the disease. The quoted sentences say what the papers report.
glioblastoma (10 papers, 2013 to 2022). The most malignant astrocytic tumor (WHO grade IV). "Previous studies have shown that a reduced expression of RIOK2 caused proliferation inhibition, apoptosis, and cell cycle arrest in Drosophila glioblastoma cells and human leukemic cells." (PMID 36361502, 2022). "Recently, RIOK2 dysregulation has been implicated in the progression of various human cancers, including that of non-small cell lung cancer, glioblastoma, hepatocellular carcinoma cells, acute myeloid leukemia and prostate cancer." (PMID 36518977, 2022). "To date, RIOK2 has been found to be highly expressed only in non-small cell lung cancer, prostate cancer, glioblastoma, acute myeloid leukemia, and hepatocellular carcinoma cells." (PMID 36518977, 2022). "Several recent studies have described the effect of pharmacological inhibition of RIOK2 expression in prostate cancer, glioblastoma, and acute myeloid leukemia (AML)." (PMID 36661680, 2022). "RIOK2 was previously confirmed to be highly expressed and over-activated in non-small cell lung cancer, prostate cancer, and glioblastoma, driving the occurrence and development of related tumors." (PMID 36518977, 2022). "Existing evidence has shown that RIOK2 is involved in non-small cell lung cancer, glioblastoma, hepatocellular carcinoma, acute myeloid leukemia, and prostate cancer progression." (PMID 36518977, 2022). "In agreement with this, RIOK2 is required for cell proliferation, migration and survival of glioblastoma." (PMID 34125833, 2021). "A study by Read and colleagues investigated a Drosophila glioblastoma model and discovered the Akt-dependent overexpression of RIOK1 and RIOK2 in glioblastoma cells." (PMID 33383959, 2020). "Our results revealed that the atypical kinases RIOK1 and RIOK2 are overexpressed in glioblastoma cells in an Akt-dependent manner." (PMID 23459592, 2013). "To further validate whether RIOK2 mediated the inhibitory effects of NSC139021 on glioblastoma cell proliferation, we silenced RIOK2 by using gene-specific siRNAs in U118MG and LN-18 cells." (PMID 34572430, 2021). "RIOK1 and RIOK2 have been shown to drive proliferation and survival in glioblastoma cells." (PMID 32125767, 2020). "RIO kinase 2 has emerged as a critical kinase for ribosome maturation, and recently it has also been found to play a fundamental role in cancer, being involved in the occurrence and progression of glioblastoma, liver cancer, prostate cancer, non-small cell lung cancer, and acute myeloid leukemia." (PMID 36518977, 2022). "A previous study reported that RIOK2 formed complexes with RIOK1 and mTOR and then enhanced the Akt-signaling pathway in glioblastoma." (PMID 36661680, 2022). "We verified that NSC139021 effectively inhibited glioblastoma cells proliferation, but it is independent of RIOK2." (PMID 34572430, 2021). "In addition, RIOK2 and RIOK1 are highly expressed in glioblastoma cells, overexpression of RIOK1/2 promotes cell proliferation, and down‐regulation of RIOK1/2 causes apoptosis and increased sensitivity to chemotherapy." (PMID 32125767, 2020). "Thus, NSC139021 suppressed viability and proliferation of human glioblastoma cells was independent of RIOK2." (PMID 34572430, 2021).
glioblastoma (continued). "Here, we investigated the anti-glioblastoma effects of RIOK2 inhibitor NSC139021 and found that it inhibited the viability and proliferation of human and mouse glioblastoma cells via a mechanism independent of RIOK2 and other RIO kinases." (PMID 34572430, 2021).
glioma (8 papers, 2013 to 2024). A benign or malignant brain and spinal cord tumor that arises from glial cells (astrocytes, oligodendrocytes, ependymal cells). "Silencing RIOK2 inhibits the migration, invasion, and epithelial-mesenchymal transition of glioma cells, while overexpression of RIOK2 promotes these processes." (PMID 38699234, 2024). "The association of RIOK2 with bystin-like protein and mechanistic target of rapamycin kinase promotes tumor cell growth and survival through activation of AKT signaling in gliomas." (PMID 36518977, 2022). "Mechanistically, BYSL activated the AKT pathway by regulating RIOK2 and mTOR, acting as an oncogene in gliomas." (PMID 35473611, 2022). "We next established lentivirus-mediated glioma cell lines that exhibited stable overexpression/downregulation of RIOK2." (PMID 33628587, 2021). "We identified a complex consisting of BYSL, RIOK2, and mTOR, and observed co-localization and positive correlations between BYSL and RIOK2 in glioma cells and tissues." (PMID 33628587, 2021). "More importantly, the inhibitory effects of miR‐4744 on glioma cell migration and invasion were rescued by the overexpression of RIOK2." (PMID 32125767, 2020). "We confirmed that miR‐4744 directly bound to the 3'‐UTR of RIOK2 and negatively regulated RIOK2 expression in glioma cells." (PMID 32125767, 2020). "The present study provides a novel strategy for targeting RIOK2 using small RNAs in the treatments of glioma." (PMID 32125767, 2020). "Transwell invasion assay and qRT‐PCR detection of matrix metalloproteinases (MMPs) were used to evaluate the effects of down‐regulation of RIOK2 on glioma cell invasion." (PMID 32125767, 2020). "Collectively, these results revealed upstream and downstream signalling pathways involved in RIOK2‐mediated glioma cell migration and invasion." (PMID 32125767, 2020). "The expression of RIOK2 was down‐regulated in glioma cells by transfection of RIOK2 siRNAs (si‐RIOK2‐2 and si‐RIOK2‐4)." (PMID 32125767, 2020). "In this study, we first studied the role of RIOK2 in glioma cell migration, invasion and EMT process using small interfering RNA (siRNA) and overexpression lentivirus of RIOK2." (PMID 32125767, 2020). "Next, we used wound healing and Transwell assays to assess the effects of down‐regulation of RIOK2 on glioma cell migration." (PMID 32125767, 2020). "Here, we reported that RIOK2 contributed to the migration and invasion in glioma cells, which offers a significant supplement for the common functions of RIO kinases in tumour growth and expansion." (PMID 32125767, 2020). "MiR‐4744 was found to directly bind to the 3'‐UTR of RIOK2 and negatively regulated RIOK2 expression in glioma cells." (PMID 32125767, 2020). "In summary, knockdown of RIOK2 by siRNAs inhibited the migration, invasion and EMT in glioma cells, while overexpression of RIOK2 showed the opposite effects." (PMID 32125767, 2020). "We next used wound healing and Transwell migration assays to assess the influence of overexpression of RIOK2 on the migration of glioma cells." (PMID 32125767, 2020). "In this study, we demonstrated that RIOK2 played a promoting role in glioma cell migration and invasion and EMT progression." (PMID 32125767, 2020). "Some tumor-suppressive miRNAs can also target RIOK2 expression in lung cancer and glioma." (PMID 36661680, 2022). "In addition, experiments with a glioma orthotopic xenograft model showed that silencing BYSL or RIOK2 decreased the growth of tumors and prolonged the survival times of tumor-bearing mice." (PMID 33628587, 2021). "Indeed, the overexpression of BYSL caused a significant increase in the protein levels of RIOK2, AKT, PARS40, mTOR, P70S6K, and S6 in glioma cells." (PMID 33628587, 2021). "Finally, intracranial xenograft experiments confirmed the oncogenic roles of BYSL and RIOK2 in glioma growth." (PMID 33628587, 2021).
glioma (continued). "In addition, BYSL is co-expressed with RIOK2 in glioma cells and is positively correlated with RIOK2 at both the gene and protein levels in glioma tissues." (PMID 33628587, 2021). "As for the glioma subgroups, the up‐regulation of RIOK2‐mRNA was mostly attributed to Grade III (P = .035) and Grade IV groups (P = .059), while the down‐regulation of miR‐4744 level was mainly based on Grade II (P = .116) and Grade III (P = .060) glioma tissues." (PMID 32125767, 2020). "The low miR‐4744 and high RIOK2 levels in glioma tissues may contribute to cell migration and invasion through promoting the transition from epithelial cells to mesenchymal phenotype." (PMID 32125767, 2020). "RIOK2 was forced to expression in glioma cells by lentivirus‐mediated infection." (PMID 32125767, 2020). "In addition, RIOK2 and miR‐4744 levels were quantified by qRT‐PCR and/or immunohistochemistry in glioma tissues." (PMID 32125767, 2020). "A recent study identified RIOK2 silencing in glioma cells inhibited cell migration and invasion." (PMID 33383959, 2020). "In order to verify whether miR‐4744 affects glioma cell migration and invasion through regulating RIOK2, we performed the following rescue experiments." (PMID 32125767, 2020). "In addition, the mechanism by which RIOK2/miR‐4744 regulates the EMT process deserves further studies in glioma cells." (PMID 32125767, 2020). "Furthermore, we found that miR‐4744 inhibited the migration, invasion and EMT process in glioma cells, and overexpression of RIOK2 partially reversed the suppressed effects of miR‐4744 on cell migration, invasion and EMT." (PMID 32125767, 2020). "Evidence has accumulated that RIOK2 is connected with diverse cellular processes in cancer development and progression, such as cellular proliferation, migration, invasion, and apoptosis For example, RIOK2 promotes glioma cell migration and invasion through epithelial–mesenchymal transition." (PMID 36518977, 2022). "Therefore, miR‐4744 may inhibit cell migration and invasion by targeting RIOK2, which should be validated in patient‐derived glioma cell lines in the future." (PMID 32125767, 2020). "Because BYSL, RIOK2, and mTOR existed in the same complex, we next identified the role of BYSL in regulating RIOK2, AKT, and mTOR signaling in glioma cells." (PMID 33628587, 2021). "However, the role and mechanism of RIOK2 in glioma cell migration and invasion remain unclear." (PMID 32125767, 2020). "Recent studies have reported RIOK2 overexpression in non-small-cell lung cancer (NSCLC) and glioma." (PMID 36661680, 2022). "In addition, endogenous mTOR co-immunoprecipitated with RIOK2 and BYSL in BYSL-overexpressing cells and endogenous BYSL co-immunoprecipitated with RIOK2 and mTOR in U251 glioma cells." (PMID 33628587, 2021). "Both BYSL and RIOK2 positively regulated AKT/mTOR signaling, which might be responsible for the promoting effects of BYSL on human glioma growth." (PMID 33628587, 2021). "Western blot analysis of our cohorts also showed a significantly positive correlation between BYSL and RIOK2 expressions in glioma tissues (n = 33, R = 0.608, P < 0.001) but not in nontumor brain tissues (n = 9, R = 0.377, P = 0.317)." (PMID 33628587, 2021). "Furthermore, we found a significantly positive correlation between BYSL and RIOK2 gene expressions in LGG (R = 0.49, P = 1.3e-32), GBM (R = 0.30, P = 7.8e-05), and various grades of glioma tissues (R = 0.253, P = 2.7e-05) by analyzing public datasets." (PMID 33628587, 2021). "Here, we found that overexpressing RIOK2 elevated the expression of N‐cadherin, β‐catenin, Twist1, fibronectin and ZEB‐1, whereas the miR‐4744 mimics treatment showed the opposite effects in glioma cells." (PMID 32125767, 2020). "When the outliers were removed, however, we found a significant increase in the RIOK2 mRNA level (P = .010) and a significant decrease in the miR‐4744 level (P = .025) in the pooled glioma group as compared to the nontumour group." (PMID 32125767, 2020).
glioma (continued). "Overexpression of RIOK2 could reverse the effects of miR‐4744 up‐regulation on the migration, invasion and EMT process in glioma cells." (PMID 32125767, 2020). "Overall, overexpression of RIOK2 could rescue the effects of up‐regulation of miR‐4744 on the migration, invasion and EMT process in glioma cells." (PMID 32125767, 2020). "Transfection of RIOK2 siRNAs significantly inhibited glioma cell migration and invasion and down‐regulated the expression of MMPs (MMP2 and MMP9) and mesenchymal markers (N‐cadherin, β‐catenin, Twist1, fibronectin, ZEB‐1) in glioma cells." (PMID 32125767, 2020). "The increase of RIOK2 at both mRNA and protein levels and the inverse correlation between RIOK2‐mRNA and miR‐4744 in glioma tissues provided supporting evidence for the negative regulation of miR‐4744 on its target gene RIOK2 as we demonstrated in vitro." (PMID 32125767, 2020). "RIOK2 was recently identified in an RNAi-based screen for kinases that are required for survival of glioma stem-like cells, which confirms our results, although the functionality of RIOK2 in glioma was not explored." (PMID 23459592, 2013). "Moreover, there was a negative correlation between miR‐4744 level and RIOK2 mRNA level in the pooled glioma group (rho = −0.456, P = .025), and the negative correlation still existed when the outlier was removed (rho = −0.401, P = .058)." (PMID 32125767, 2020). "Mechanically, RIOK2 was post‐transcriptionally targeted by miR‐4744, overexpression of RIOK2 could reverse the effects of miR‐4744 up‐regulation on the migration, invasion and EMT in glioma cells." (PMID 32125767, 2020). "Finally, RIOK2 expression was found to up‐regulate at both mRNA and protein levels, while miR‐4744 level was down‐regulated in glioma tissues, and a negative correlation was found between them." (PMID 32125767, 2020). "In addition, RIOK2 expression was up‐regulated, while miR‐4744 level was down‐regulated in glioma tissues, and a negative correlation was found between them." (PMID 32125767, 2020). "Moreover, RIOK2 was high, while miR‐4744 was low in glioma tissues, and a negative correlation was found between them." (PMID 32125767, 2020).
acute myeloid leukemia (4 papers, 2022 to 2024). Acute myeloid leukemia (AML) is a group of neoplasms arising from precursor cells committed to the myeloid cell-line differentiation. "RIOK2 is closely associated with acute myeloid leukemia, myelodysplastic syndrome, and chronic kidney disease." (PMID 38699234, 2024). "Additionally, we have previously identified RIOK2 as a regulator of protein synthesis and a potential target for the treatment of acute myeloid leukemia (AML)." (PMID 38564577, 2024).
prostate carcinoma (4 papers, 2013 to 2022). A carcinoma that arises from epithelial cells of the prostate gland. "Our results may have broad relevance to other cancers since RIOK2 is strongly expressed in a range of other more common tumor types associated with high Akt activity, such as breast and prostate cancers." (PMID 23459592, 2013). "Several reports have indicated that inhibition of RIOK2 expression induced ribosomal stress in prostate cancer and ribosome dysfunction in AML." (PMID 36661680, 2022). "Previously, NSC139021 was reported to exert its anti-tumor effects by directly interacting with RIOK2 and inducing ribosomal stress in prostate cancer." (PMID 34572430, 2021).
COVID-19 (2 papers, 2024 to 2025). A disease caused by infection with severe acute respiratory syndrome coronavirus 2. "Four upregulated common genes (DHX15, USP14, COPS3, TYK2) and one downregulated common feature gene (RIOK2) were identified and showed good diagnostic accuracy for T2DM and COVID-19." (PMID 38699234, 2024). "We identified five common feature genes between T2DM and COVID-19: DHX15, USP14, COPS3, TYK2, and RIOK2 (where DHX15, USP14, COPS3, and TYK2 were upregulated and RIOK2 was downregulated)." (PMID 38699234, 2024). "We identified five common feature genes (DHX15, USP14, COPS3, TYK2, and RIOK2) and their co-regulatory pathways between T2DM and COVID-19, which may provide new insights for further molecular mechanism studies." (PMID 38699234, 2024). "The roles of DHX15, USP14, COPS3, TYK2, and RIOK2 in T2DM and COVID-19 remain primarily unknown, emphasizing the importance of future research." (PMID 38699234, 2024). "We identified five common feature genes (DHX15, USP14, COPS3, TYK2, and RIOK2) and their co-regulatory pathways between T2DM and COVID-19, which may provide new insights for molecular mechanism studies." (PMID 38699234, 2024).